CCND1 (cyclin D1)
Diseases named in the same sentence as CCND1 in open-access papers (continued):
Sharing a sentence is not in itself a finding about the gene and the disease.
breast cancer (continued). "In addition, p70S6K plays an important role in metastasis by regulating key proteins such as cyclin D1, PDCD4 and FAK, whereas E-cadherin, β-catenin and TG2 are essential for cell attachment, survival, and invasion, as well as metastasis in breast cancer." (PMID 25333576, 2015). "The resistance of cyclin D1−/−/MMTV-ErbB2 mice to ErbB2 driven mammary tumors is thought to be dependent on a complete absence of PI mammary cells in cyclin D1-null mice." (PMID 25940700, 2015). "qRT-PCR analysis of mammary tumors demonstrated increased β-catenin transcriptional activity as judged by enhanced mRNA expression of β-catenin target genes (Cyclin D1, c-Myc, TCF-7, VEGF and MMP7) in the absence of VDR." (PMID 26008979, 2015). "Our finding that HNK modulates Akt, GSK3β, and β-catenin, key components of leptin-signaling network in breast cancer cells, prompted us to further explore whether HNK treatment can also inhibit MTA1, Wnt1, β-catenin and cyclin D1 in the presence of leptin." (PMID 26036628, 2015). "Given that TSC down-regulated the expression of ERα and its downstream target gene Cyclin D1 in regular media, we suspected that TSC may suppress breast cancer cell growth by blocking the pro-proliferative function of estrogen." (PMID 25101695, 2014). "To further characterize the role of ERα in TSC-induced Cyclin D1 expression down-regulation and growth arrest in ERα-positive breast cancer cells, we knocked down ERα in MCF7 by siRNA, treated the cells with TSC, and examined the Cyclin D1 levels and cell viability." (PMID 25101695, 2014). "Remarkably in the Kunming mouse model, loss of estrogen and progesterone receptors and low expression of Her2/neu and overexpression of c-Myc, cyclin D1 and VEGF were observed, which is recapitulated in a manner similar to that observed in human breast cancer with poor prognosis." (PMID 25230850, 2014). "Indeed, among Notch targets several are also Pin1 substrates (e.g. cyclin D1, NF-κB, Survivin), suggesting that in addition to its role in sustaining Notch1 protein levels, Pin1 could promote breast cancer aggressiveness also by enhancing the activity of some Notch-induced Pin1 targets." (PMID 24357640, 2014). "To confirm whether the results obtained in breast cancer cell lines could also be observed in human primary breast tumors, we examined the expression of TBLR1, cyclin D1 and β-catenin in 10 freshly prepared breast cancer tissues." (PMID 25341494, 2014). "Depletion of RPL24 in breast cancer cells by >70% reduced cell viability by 80% and decreased protein expression of the eIF4E-dependently translated proteins cyclin D1 (75%), survivin (46%) and NBS1 (30%) without altering GAPDH or beta-tubulin levels." (PMID 24970821, 2014). "In addition, MIR17HG overexpression was found to inhibit proliferation of luminal breast cancer cells by targeting a steroid receptor coactivator (NCOA3), cyclin D1 (CCND1) and estrogen receptor α (ESR1)." (PMID 25069832, 2014). "Specifically MMTV-TGF-α mice crossed with leptin deficient mice fail to develop tumors and treatment with a leptin antagonist decreases the growth of murine triple-negative breast tumors and 4T1 mammary cancer cell growth via reducing levels of VEGF, pSTAT3 and cyclin D1." (PMID 25360510, 2014).
breast cancer (continued). "Accordingly, we conclude that CG0009 is an effective therapeutic agent for breast cancer, regardless of functional ER status, and cyclin D1 overexpression is an unfavorable response marker for the agent." (PMID 23565238, 2013). "We propose that, in ERα-positive breast cancer cells, the ratio of acetylated H2A.Z/H2A.Z rather than the total amount of H2A.Z bound to the CCND1 promoter correlates with transcriptional activity." (PMID 23637611, 2013). "Also CCND1 expression, reportedly down-regulated in breast cancer, was confirmed in our profile, through the down-regulation of MYC, reported to be coupled with CCND1 expression." (PMID 23405235, 2013). "The function of cyclin D1 in mammary oncogenesis in mice is mediated through the activation of its regulatory partner CDK4, as mice lacking CDK4 or expressing the CDK4/CDK6-specific inhibitor INK4A are resistant to HER2-induced mammary tumor formation." (PMID 23786849, 2013). "The amplification of CCND1 and the overexpression of the cyclin D1 protein frequently occur in breast cancer, although overexpression of the protein is not always due to gene amplification." (PMID 23336272, 2013). "In view of the finding that CG0009 inhibits the proliferation of ERα-negative breast cancer cells, we further investigated its effect on the cyclin D1 protein level." (PMID 23565238, 2013). "For instance, cyclin D1 expression did not correlate with Ki67 expression in a cohort of 779 breast cancer patients." (PMID 23786849, 2013). "Our data indicate that CG0009-mediated growth suppression and death are largely driven via cyclin D1 depletion in breast cancer cells, regardless of the ERα status." (PMID 23565238, 2013). "Furthermore, cyclin D1 is required for many oncogenes, such as HER2 or Ras, to induce mammary tumor growth in mice." (PMID 23786849, 2013). "In the present work, we assessed the expression of cyclin D1, CDK4 and p16 in human invasive ductal mammary carcinoma samples, correlated the findings with the known prognostic factors for breast cancer and investigated the correlations of these three markers with survival functions." (PMID 23336272, 2013). "The purpose here was to correlate the immunohistochemical expression of cyclin D1, CDK4 and p16 with the main clinical prognostic factors for breast cancer: tumor stage, nodal status, tumor grade, steroid receptors (ER and PR), HER2 status and proliferation rate." (PMID 23336272, 2013). "CCND1 is stabilized by RAS effector signaling and implicates CDK activity as one important component of the hyperactive RAS signaling pathways commonly observed in breast cancer." (PMID 23390492, 2013). "Sites within the fourth intron of CCND1 (Cyclin D1) and the Greb1 (growth regulation by oestrogen in breast cancer 1) promoter were used as negative and positive control, respectively, for FOXA1 binding." (PMID 24265722, 2013). "In addition to CCND1/CDK4 complexes, over-expression of CCND1 also leads to accumulation of activated CCND1/CDK2 complexes in breast cancer cells." (PMID 23390492, 2013). "Literature reports revealed that miR-195 could inhibit cell invasion by inhibiting CCND1 and CCND3 in breast cancer cells and gliobalstoma cells." (PMID 22723898, 2012). "Amplification of HER2, C-MYC and CCND1 seems to play a role in the early development of breast cancer, but not in its progression." (PMID 22863309, 2012). "Treatment of the MDA-MB-231 breast cancer cell line with APN resulted in the phosphorylation of Akt and in the deactivation of GSK-3β, which subsequently decreased β-catenin expression as well as the transcriptional target of β-catenin, cyclin D1." (PMID 23691481, 2012). "Amplification of HER2, C-MYC and CCND1 therefore seems to play a role in the early development of breast cancer, but not in the progression of DCIS to invasive carcinomas." (PMID 22863309, 2012). "The two genes with particular significance for breast cancer are HER-2/neu (erbB2) and cyclin D1." (PMID 22701509, 2012).
breast cancer (continued). "RT-PCR and Western blot data indicated significant (p<0.05) induction of both cyclin D1 and p21 expressions in rat mammary tumors compared with normal tissue from the control group." (PMID 23508728, 2012). "We next compared cyclin D1 expression and the highest ranking CIN genes to a breast cancer expression database and discovered that expression of genes promoting CIN are highly enriched in luminal subtype and that high cyclin D1 and CIN expression correlate specifically in the luminal B subtype." (PMID 22538871, 2012). "The HER2, C-MYC, CCND1 and FGFR1 amplification status was in most cases concordant in the matched invasive and DCIS components of the same tumors, pointing to early roles in the development of breast cancer." (PMID 22863309, 2012). "We have previously shown that cyclin D1 silencing increases migration of the ER-negative MDA-MB-231 breast cancer cell line, an effect not observed when silencing its binding partners CDK 4/6." (PMID 21955753, 2011). "More recently, a number of cyclin D1 studies in breast cancer have focused on functions that are not directly related to cell cycle maintenance." (PMID 21955753, 2011). "In other cancer types, such as breast cancer, the peak amplification in this region may be different, targeting EMSY and/or CCND1." (PMID 20844748, 2010). "Although cyclin D1 levels were increased in Wnt1 tumors compared with normal mammary epithelium, we found an additional fourfold increase in the cyclin D1 level in Wnt/ILK double-transgenic mammary tumors." (PMID 20565980, 2010). "Because cyclin D1 is induced with an exogenous source of AGR2 and reduced with an anti-AGR2 Ab, and AGR2 is detected in the supernatant of breast cancer cell lines, it suggests that AGR2 may have an extracellular mechanism of action." (PMID 20525379, 2010). "The CCND1 gene has a SOX2-binding sequence in its promoter, and chromatin immunoprecipitation has revealed SOX2 and beta-catenin cooperative binding regulating this promoter in breast cancer cell lines." (PMID 20548776, 2010). "This study shows that the aggressive breast cancers overexpress cyclins A, B1 and E whereas cyclin D1 expression is independent of the other cyclins." (PMID 19615042, 2009). "Taken together, we conclude that the development of malignant breast tumors in either WT or MMTV-cyclin D1 mice was not increased due to overexpression of human cortactin." (PMID 16536875, 2006). "Ninety genes belonging to the GO category of 'apoptosis', including members of the BAG family (BAG1, BAG2, BAG3), as well as members of the breast cancer 'proliferation signatures' (BUB1, PLK1, CCNE1, CCND1 and CCNB1) were also identified as up-regulated in our DTET." (PMID 17014703, 2006). "No randomised clinical studies detailing cyclin D1 in ERα positive breast cancer with regards to tamoxifen response have been reported." (PMID 15138475, 2004). "The present study also indicates that overexpression of cyclin D1 does not affect the outcome of tamoxifen treatment of early stage, OR-α positive breast cancer." (PMID 11875707, 2002). "Overexpression of cyclin D1 was not prognostic value for recurrence of survival in a consecutive series of 248 operable breast cancer patients (stage I and II)." (PMID 8611372, 1996). "Beyond glioblastoma, the authors observed that RBBP4 knockdown significantly reduced cyclin D1 expression in hepatocellular carcinoma, colorectal cancer, and breast cancer cell lines (data not shown), further supporting the importance of RBBP4 in regulating gene expression across various tumors." (PMID 40187236, 2025).
breast cancer (continued). "Based on the findings of a 2017 report by Ahlin and colleagues, it was demonstrated that only in patients with ER + breast cancer (and not in those with ER- disease), the elevated expression of cyclin D1 is correlated with increased cell proliferation and a three-fold higher death risk." (PMID 38850382, 2024). "Hence, we propose that the combination of ER and PRMT5 inhibitors can synergistically block the G1-to-S transition in ER+/RB-deficient breast cancer, independent of the CDK4/6/Cyclin D1 complex." (PMID 38480701, 2024). "We hypothesized that CCND1 and CCNE1 activation could represent a mechanism for palbociclib resistance in HNSCC, considering recent clinical data showing high CCNE1 as worse clinical outcome for palbociclib-treated patients in breast cancer." (PMID 38954773, 2024). "Such a regulatory mechanism has been observed in, e.g., breast cancer, where high CRNDE expression diminished the level of miR-136, thus activating the Wnt/β-catenin pathway, contributing to the up-regulation of c-Myc and cyclin D1 and resulting in increased rate of cancer cell proliferation." (PMID 38673965, 2024). "miR-34a inhibited cyclin D1 expression in the non-small-cell lung cancer A549 cell line, prostate cancer PC3 cells, several oesophageal squamous cell carcinoma cell lines, the human breast cancer cell line MCF-7 and the human laryngeal carcinoma cell line HEp-2." (PMID 37831728, 2023). "Hence, we propose that the combination of ER and PRMT5 inhibitors can synergistically block the G1-to-S transition in ER+/RB-deficient breast cancer, and this effect is independent of the CDK4/6/Cyclin D1 complex." (PMID 37502925, 2023). "Interesting, insights from breast cancer cell research revealed that SFN orchestrates DNA methylation through the modulation of DNA methyltransferase and histone deacetylase levels, coupled with the downregulation of cyclin D1, CDK4, and pRB, thereby promoting breast cancer cell apoptosis." (PMID 37836745, 2023). "However, many studies demonstrated that the overexpression of Cyclin D, with or without Cyclin D1 gene amplification, occurred in more than 50% of breast cancer cells." (PMID 36900131, 2023). "Thus, circ_6014 could influence breast cancer cellular proliferation via regulation of the cell cycle through changes in CDK2/CCNE1 and CDK4/6/CCND1 cell cycle proteins and regulation of the G0/G1 phase of the cell cycle." (PMID 35383130, 2022). "However, GluOC had no obvious effect on the PCNA and cyclin D1 protein levels in MCF7 breast cancer cells." (PMID 35413833, 2022). "Supporting this are observation that high Cyclin D1 expression levels correlate with long-term prognosis in ILC, and the finding that the CDK4/6 inhibitor abemaciclib induces upregulation of Cyclin D1 in luminal-type ER+ and lobular-type breast cancer cell lines." (PMID 35437308, 2022). "Among this PPI network, PTEN, CCND1, VEGFA, CDC42, and EZH2 were ranked as the top five hub genes, which may function as key genes in the m5C regulators-related miRNA–mRNA regulatory network in breast cancer." (PMID 35812757, 2022). "The importance of leptin-induced autophagy in ER+ breast cancer cells relies on leptin-induced cancer cell proliferation, as autophagy was shown to participate in the negative regulation of the transcriptional factor E2F1, enabling leptin-mediated cyclin D1 expression." (PMID 36291097, 2022). "Furthermore, a higher CCND1 amplification rate was also detected in TPBC compared with HR-negative, HER2-positive breast cancer, and more than 80% of TPBC were characterized by luminal A/B intrinsic subtype, indicating the sensitivity of TPBC to CDK4/6 inhibitor and endocrine therapy." (PMID 36396665, 2022). "Interestingly, parkin mRNA and protein expression are significantly decreased in breast cancer, but no significant changes in cyclin D1 and cyclin E levels are observed, while cyclin-dependent kinase 6 (CDK6) expression level is significantly increased." (PMID 36147481, 2022).
breast cancer (continued). "CCND1 overexpression was not sufficient to induce doxorubicin resistance in CCND1-neutral breast cancer cell lines, nor did CCND1 knock-down increase doxorubicin sensitivity in CCDN1-amplified cell lines, suggesting that CCND1 is not the sole driver of doxorubicine resistance in this setting." (PMID 35523804, 2022). "In MCF-7 breast cancer cells, apelin-13 induces the transcription of the hormone-dependent breast cancer amplified 1 (AIB1), which promotes the activation of ERK, favoring the expression of cyclin D1 and the secretion of MMP-1, leading to an increase in cell proliferation and invasion." (PMID 36291097, 2022). "Besides, seven genes including BRCA1, FN1, CCNE1, CCND1, CHEK1, BUB3, and CDC25A were identified as the hub nodes by the PPI network, and CCNE1 and CHEK1 were confirmed to be related with the prognostic survival of the patients with breast cancer." (PMID 35186236, 2022). "Additionally, HSP suppressed aromatase enzyme activity, cyclin D1, CDK4, Bcl-xL, pS2 and induces CCAAT/C/EBP, pERK-1&-2, p57Kip2 expression, which contributes to reducing the tumour growth in MCF-7 breast cancer cells and female athymic mice model both in vivo and in vitro." (PMID 35128104, 2022). "However, 6-shogaol induces autophagic cell death in breast cancer cells and CSC-like spheroids via γ-secretase mediated down-regulation of Notch signaling (reduction in the expression levels of cleaved Notch1 and its target proteins Hes1 and Cyclin D1)." (PMID 34575981, 2021). "However, in obese breast cancer patients, the low expression level of adiponectin makes it a growth factor that acts on ER-α-positive MCF-7 breast cancer cells and upregulates the expression of cyclin D1 in the cells." (PMID 34485124, 2021). "Previous studies show that atRA inhibits cell proliferation through downregulation of cyclin D1 (CCND1) and upregulation of cyclin-dependent kinase inhibitor 1B (CDKN1B; a.k.a. p27, KIP1) in HEPM cells as well as in MCF-7 cells, a human breast cancer cell line." (PMID 33585479, 2021). "Besides, knockdown of MRC2 in human breast cancer cell lines: MCF7, MDA-MB-231, and MDA-MB-436 could also decelerate the cell proliferation, and reduce the mRNA levels of proliferation markers CCND1 and MKI67." (PMID 34815798, 2021). "In addition, increased cyclin D1 expression has been reported in pancreatic, colorectal, head and neck squamous cell, as well as endometrial carcinoma and NSCLC, while cyclin D1 overexpression or amplification is frequently found in breast cancer." (PMID 34361615, 2021). "Indeed miR-34a may affect positively in the modulation of drug sensitivity in breast cancer by suppression of NOTCH1, BCL-2, and CCND1." (PMID 33773546, 2021). "Furthermore, in ER+ve breast cancer models, dihydrotestosterone (DHT)-mediated activation of AR has been shown to inhibit ER-α signaling and cell cycle progression through a reduction in CCND1 transcription." (PMID 33777765, 2021). "No prognostic impact of cyclin D1 expression was found among the ER+ breast cancers." (PMID 32210163, 2020). "However, the suppression of ERK1/2 phosphorylation by PD98059 in the 2 breast cancer cell lines had no clear effects on the expression of p-Ser9–GSK3β and the abundance of Cyclin D1." (PMID 32944401, 2020). "In our recent report, increasing LPP1 in MDA-MB-231 breast cancer cells decreases the levels of c-Jun and c-Fos in nuclei and suppresses the expression of AP-1 (activator protein 1) -regulated genes including MMPs (matrix metalloproteinases) and CCND1/3 (cyclin D1/D3)." (PMID 32887262, 2020). "In addition to exerting E2-like effects, studies with ER-positive breast cancer cells show BPA antagonizes the proapoptotic effects of tamoxifen while favoring transition of cell cycle from G1 to S phase, and upregulating cyclin D1 (CCND1) and ERα." (PMID 33330580, 2020).